PDGFRB (platelet derived growth factor receptor beta)
Diseases named in the same sentence as PDGFRB in open-access papers (continued):
Sharing a sentence is not in itself a finding about the gene and the disease.
mastocytosis (8 papers, 2013 to 2021). A clonal myeloproliferative neoplasm characterized by the proliferation and accumulation of neoplastic mast cells in one or multiple organs or organ systems. "Further studies may be of benefit to determine if PRKG2/PDGFRB fusion is harbored by mast cells, which would suggest that the cases thus far described may represent a distinct clonal disorder, rather than a systemic mastocytosis with a second non-mast cell hematologic disorder." (PMID 27648315, 2016).
schwannoma (8 papers, 2012 to 2020). A benign, usually encapsulated slow growing tumor composed of Schwann cells. "Analysis of phospho-receptor tyrosine kinase and phospho-kinases proteome profiler arrays revealed that schwannomas consistently had higher levels of phosphorylated PDGFRα, PDGFRβ, SRC, MEK and STAT3 compared with control primary HSC." (PMID 28427224, 2017). "Schwannomas exhibited averaged 6.6 times higher PDGFRα phosphorylation, 5.4 times higher PDGFRβ phosphorylation, 30 times higher SRC phosphorylation, 5.6 times higher MEK phosphorylation and 7.4 times higher STAT3 phosphorylation compared with control primary HSC." (PMID 28427224, 2017). "Previous studies demonstrated that overexpression and activation of PDGFRβ strongly activates MEK1/2 and ERK1/2 in human schwannoma cells leading to enhanced proliferation." (PMID 28427224, 2017). "Schwannoma cell lines lacking the tumor suppressor activity of merlin have high basal levels of phosphorylated extracellular signal-regulated kinase (ERK1/2) and AKT, which are activated by the Src/FAK/Ras and PI3K/Raf signaling cascades and platelet-derived growth factor receptor beta (PDGFRβ)." (PMID 24393766, 2014).
systemic sclerosis (8 papers, 2014 to 2025). A chronic disorder, possibly autoimmune, marked by excessive production of collagen which results in hardening and thickening of body tissues. "In fact, an early study showed that PDGFRβ is highly expressed in fibroblasts in skin biopsies of systemic sclerosis (SS) patients, and a recent scRNA-seq analysis identified ITGA11 as enriched in SS skin myofibroblasts." (PMID 36003785, 2022).
hemangiosarcoma (7 papers, 2010 to 2025). "On the other hand, expression of PDGFRβ, CD44, and EPHA2 in hemangiosarcoma cell lines was not predictive for the expression of these proteins in tumor tissues, and a similar trend was observed for Neuropilin 1 and v-Myc." (PMID 21062482, 2010).
Hyperglycemia (7 papers, 2014 to 2024). An increased concentration of glucose in the blood. "A study suggested that platelet derived growth factor receptor beta polypeptide (Pdgfrb) expression were decreased in maternal hyperglycemia compared to controls in animal model." (PMID 36544488, 2022). "In hyperglycemia, protein kinase C-delta (PKC-δ) upregulation inhibits the PDGF/PDGFRβ-Αkt pathway, reducing pericyte survival and inducing pericyte apoptosis." (PMID 36781980, 2023). "Taken together, these results indicated that pericytes in T1KO mice were more resistant to PDGFRβ antibody than those in WT mice, suggesting that the vascular system in T1KO mice is more resistant to certain external stresses, such as hyperglycemia, compared to that in WT mice." (PMID 38595797, 2024).
liposarcoma (7 papers, 2016 to 2025). A usually painless malignant tumor that arises from adipose tissue. "In addition, the association between the expression of platelet-derived growth factor receptor beta (PDGFRβ) and Ki67 labeling index has been reported in canine liposarcomas." (PMID 40271490, 2025). "In summary, we demonstrate that miR-193b controls cell growth and differentiation in liposarcoma by targeting multiple key components (PDGFRβ, SMAD4, and YAP1) in several oncogenic signaling pathways." (PMID 30824765, 2019). "Restoring miR-193b activity or inhibition of PDGFRβ or Wnt/β-catenin signaling could represent a new therapeutic strategy in liposarcoma." (PMID 30824765, 2019). "Inhibition of PDGFRβ reduces liposarcoma cell viability and increases adipogenesis." (PMID 30824765, 2019). "Considering the potential interaction among PDGFRβ, SMAD4, and YAP1 in precipitating cancer development, inhibiting these targets by miR-193b can therefore help halt liposarcoma progression." (PMID 39736850, 2025).
lymph node metastasis (7 papers, 2016 to 2025). "High expression of PDGFRB was associated with lymph node metastasis (p = 0.012) and lymphovascular invasion (p = 0.047)." (PMID 32235327, 2020). "High expression of PDGF, PDGFRA, and PDGFRB were remarkably associated with lymph node metastasis and poor OS, as determined by immunohistochemistry." (PMID 32235327, 2020). "Elevated expression of PDGFRB was associated with lymph node metastasis and lymphovascular invasion." (PMID 32235327, 2020). "Overexpression of PDGFRA and PDGFRB is associated with lymph node metastasis and poor prognosis." (PMID 32235327, 2020). "We found positive correlations of the mRNA levels of PDGFA, PDGFB, and PDGFRB with lymph node metastasis and poor overall survival (OS)." (PMID 32235327, 2020). "Furthermore, increased levels of PDGFRB correlated significantly with lymph node metastasis (p = 0.026) and advanced TNM stage (p = 0.045)." (PMID 32235327, 2020).
myelodysplastic syndrome (7 papers, 2013 to 2025). A clonal hematopoietic disorder characterized by dysplasia and ineffective hematopoiesis in one or more of the hematopoietic cell lines. "Myeloproliferative neoplasms (MPNs) are a major subgroup of chronic myeloid neoplasms, alongside myelodysplastic syndromes (MDS), MDS/MPN overlap syndromes, and myeloid/lymphoid neoplasms, with eosinophilia associated with recurrent PDGFRA, PDGFRB, FGFR1, or PCM1-JAK2 rearrangements." (PMID 40650198, 2025).
myeloma (7 papers, 2005 to 2024). "In a preclinical study it was shown that PDGF-B/PDGFRβ pathway promoted tumor growth and vessel sprouting in multiple myeloma, and dasatinib, a PDGFRβ/Src inhibitor delayed tumor growth and angiogenesis." (PMID 27713269, 2010).
Parkinson disease (7 papers, 2023 to 2025). A progressive degenerative disorder of the central nervous system characterized by loss of dopamine producing neurons in the substantia nigra and the presence of Lewy bodies in the substantia nigra and locus coeruleus. "Future studies, including patients with Lewy body disease and Parkinson's disease with biomarker evidence of pathology, are needed to characterise the pericyte dysfunction and CSF PDGFRβ metabolism in synucleinopathies." (PMID 40239464, 2025). "However, parkinsonism associated with PDGFRB mutations in the absence of cranial CT calcifications has never been described before." (PMID 40542608, 2025). "In an animal model of Parkinson’s Disease, PDGF-BB promoted neurovascular function via PDGFRβ signaling." (PMID 37601628, 2023).
rhabdomyosarcoma (7 papers, 2016 to 2025). A rare aggressive malignant mesenchymal neoplasm arising from skeletal muscle. "PDGFRs are known to cross-talk with IGR-1R in many cancers, and PDGFRβ acts as a bypass resistance pathway to IGF-1R inhibition in rhabdomyosarcoma." (PMID 36497233, 2022). "PDGFR gene expression analysis in pediatric rhabdomyosarcoma demonstrated decreased failure‐free survival for patients with tumors that overexpressed either PDGFRα or PDGFRβ mRNA." (PMID 33474828, 2021).
scleroderma (7 papers, 2011 to 2025). Scleroderma is a rare autoimmune connective tissue disorder characterized by abnormal hardening of the skin and, sometimes, other organs. "We first studied, by immunohistochemistry, the expression of PDGFRα and PDGFRβ in scleroderma versus normal skin." (PMID 22697462, 2012). "On the contrary, PDGFRα and PDGFRβ were highly expressed in scleroderma skin." (PMID 22697462, 2012). "We found that PDGFR on spindle-like cells is highly phosphorylated in scleroderma skin, in sharp contrast to normal skin where PDGFR and phospho-PDGFR are virtually undetectable (mean ± SEM: 0.89 ± 0.02 and 0.93 ± 0.02 for phospho-PDGFRα/PDGFRα and phospho-PDGFRβ/PDGFRβ, respectively)." (PMID 22697462, 2012). "Expression of phosphorylated PDGFRα and PDGFRβ could not be detected in spindle-like cells in the dermis of normal skin; on the contrary, these receptors were highly expressed on spindle-like cells in scleroderma skin." (PMID 22697462, 2012).
asthma (6 papers, 2019 to 2025). "This study supports the thesis that PDGF-BB and PDGFRβ are presumably mostly involved in AR in asthma out of other isoforms of PDGF and PDGFR." (PMID 32116722, 2020). "Studies on asthma suggested that inhibition of PDGFRβ signaling, in the context of exposure to chronic air allergens, can lead to increased lung dysfunction and thickening of airway smooth muscles, resulting in airflow limitation." (PMID 31428169, 2019). "One of the first in vivo studies on PDGF expression pattern in humans with asthma and COPD, published in 1994, showed that PDGF(B) and PDGFRβ mRNA expression in lungs of patients with asthma did not statistically differ from healthy controls." (PMID 32116722, 2020).
diabetic nephropathy (6 papers, 2018 to 2025). "Although PDGFRβ in the glomerular mesangial cells plays a significant role in renal development and pathologies, its activation in proximal tubular epithelial cells significantly contribute to the progression of diabetic kidney disease." (PMID 39761275, 2025). "Similarly, in a rat model of diabetic kidney disease, glomerular increase in both PDGF B and PDGFRβ is found." (PMID 39761275, 2025). "Although PDGFRβ is activated in the kidneys in patients with diabetic kidney disease, the mechanism of its activation is not known." (PMID 39761275, 2025).
metastatic melanoma (6 papers, 2005 to 2023). A melanoma that has spread from its primary site to another anatomic site. "This is of interest because activation of PDGFRβ has been proposed as a mechanism of acquired resistance to vemurafenib in patients with metastatic melanoma." (PMID 36624452, 2023).
osteoporosis (6 papers, 2021 to 2025). A condition of reduced bone mass, with decreased cortical thickness and a decrease in the number and size of the trabeculae of cancellous bone (but normal chemical composition), resulting in increased fracture incidence. "Distinct from the genes previously discussed, PDGFRB, a receptor gene, plays a unique role in influencing osteoporosis." (PMID 40130165, 2025). "As an essential factor in PDGF-BB-mediated H-type vascular development in bone, the PDGFRβ/FAK signal was found to be inactivated in GCs-mediated osteoporosis." (PMID 36310171, 2022). "Identifying 8 key genes as potential regulatory target genes for the differentiation of mesenchymal stem cells into osteoblasts or adipocytes under the condition of disuse osteoporosis (ITGB3, LAMC1, COL6A3, ITGA8, PDGFRB, ITGA4, LAMB1, LAMA4)." (PMID 40130165, 2025).
Sepsis (6 papers, 2013 to 2023). Sepsis is defined as life-threatening organ dysfunction caused by a dysregulated host response to infection. "In a swine model of sepsis-induced AKI, PMT was detected within 9 h from LPS injection, as evaluated by the reduction of physiologic PDGFRβ expression and the dysfunctional α-SMA increase in peritubular pericytes." (PMID 31357597, 2019). "The present study investigated the role of the PDGFRβ/IQGAP1 pathway in EC-mediated SMC phenotypic transformation and migration during sepsis in a co-culture cell model." (PMID 31523178, 2019). "Taken together, our results suggest that the PDGFRβ/PI3K/Akt/IQGAP1 pathway is an important regulator in the recovery process induced by LPS injury and therefore plays a critical role in vascular injury during sepsis." (PMID 31576676, 2019).
serous ovarian cancer (6 papers, 2016 to 2025). "Analyses of three of the largest databases available revealed variable results regarding associations between high PDGFRB gene expression and overall survival in high-grade serous ovarian cancer." (PMID 26918345, 2016). "PDGFRβ expression is found in the majority of serous ovarian carcinomas, in particular high-grade serous cancers." (PMID 29228656, 2017).
viral infection (6 papers, 2021 to 2024). "Viral infection was first assessed using an immunostaining approach: we observed the ability of the two RVFV strains to infect at 1 day post-infection (dpi) hEC (labeled specifically with the ZO-1 TJ marker) and pericytes (labeled specifically with the PDGFRβ marker)." (PMID 39345143, 2024).
colorectal tumor (5 papers, 2020 to 2023). "Consequently, PDGFRB expression in mesenchymal colorectal tumour cell lines promotes the formation of liver metastases." (PMID 36139509, 2022). "Meanwhile, it is also correlated with CRC invasion and metastasis, for example, excessive PDGFRβ signaling leads to oversecretion of THBS4 and proliferative colorectal tumor development." (PMID 37122535, 2023). "Platelet-derived growth factor receptor β (PDGFRβ), which is a member of the PDGFR family, can also be expressed and induce primary signaling in colorectal tumor cells." (PMID 32899998, 2020).
heart failure (5 papers, 2016 to 2024). Inability of the heart to pump blood at an adequate rate to meet tissue metabolic requirements. "The PDGFRB-positive area was increased in the interstitial space around the vasa recta in patients with heart failure." (PMID 37845397, 2023). "Conditional knockout of Pdgfrβ (PdgfrβNkx2.5cre) leads to ventricular dilation with age and severe heart failure upon induction of pressure overload." (PMID 34513823, 2021).
invasive breast carcinoma (5 papers, 2019 to 2023). A carcinoma that infiltrates the breast parenchyma. "Higher expression of PDGFRb has been associated with a significantly decreased benefit from tamoxifen in ER-positive invasive breast cancer." (PMID 33661437, 2021). "Previous studies have also reported that α‐SMA and PDGFRB expression in fibroblasts has pro‐metastatic effects mostly through matrix remodeling in invasive breast cancer." (PMID 37171030, 2023). "Kruskal Wallis test revealed the significant expression (p = 5.96e-04) of the PDGFRB gene in breast invasive carcinoma compared to normal and metastatic samples." (PMID 36686654, 2022). "The role of stromal PDGFRb expression in progression and treatment response of invasive breast cancer is still not fully understood." (PMID 33661437, 2021). "PDGFRb is a key regulator of fibroblasts and mural cells and has been previously suggested, both by functional and correlative studies, to play a role in the progression and treatment response of invasive breast cancer." (PMID 33661437, 2021). "In invasive breast cancer, a comprehensive IHC analysis approach recently identified four functional different fibroblast subsets, of which one subset was high in fibroblast activation protein (FAP) and PDGFRb expression and functionally linked to immunosuppression and pro-invasive effects." (PMID 33661437, 2021). "In invasive breast cancer cells, AF1q further induced pYSTAT3 levels through the Src kinase-driven PDGFB/PDGFRB cascade." (PMID 31671695, 2019). "However, since the interaction test between PDGFRb and RT was not significant, our data does not confirm stromal PDGFRb expression as a predictive biomarker for RT benefit in early stage invasive breast cancer." (PMID 33661437, 2021).
kidney cancer (5 papers, 2015 to 2025). Primary or metastatic malignant neoplasm involving the kidney. "Data on the expression and prognostic role of PDGFRα and PDGFRβ in kidney cancer are scarce and require further research." (PMID 40434293, 2025).
oral cancer (5 papers, 2015 to 2023). "In oral cancer, a positive correlation was found between elevated PDGFRB levels and lymph node metastases." (PMID 35406617, 2022). "Moreover, PDGF ligands drive metastatic oral cancer cell line migration mediated by PDGFRβ in tumor cells." (PMID 31086173, 2019). "Among the 4 hub genes, the three genes EGFR, PDGFRB, STAT5A have already been annotated to be related to oral cancer according to GeneCards." (PMID 26064958, 2015).
Pleural effusion (5 papers, 2014 to 2025). The presence of an excessive amount of fluid in the pleural cavity. "Although the mechanism of dasatinib related pleural effusion is not fully understood, it is thought to be associated with PDGFRβ inhibition." (PMID 25276139, 2014).
prostate tumor (5 papers, 2010 to 2023). "In comparison, the high expression of PDGFRβ in prostate tumor stroma was associated with PCa aggressiveness and low patient survivability." (PMID 37631218, 2023). "The study revealed a number of novel associations between stromal PDGFRβ expression in prostate tumors and several important clinical characteristics, including survival." (PMID 20505768, 2010). "Together these findings demonstrate previously un-recognized associations between stromal and perivascular PDGFRβ expression in prostate tumors and characteristics associated with a more aggressive cancer phenotype." (PMID 20505768, 2010). "BGS were carried out in ALOX12 and PDGFRB with 5 prostate tumors and 2 BPH samples." (PMID 24626295, 2014). "PDGFRβ+ cells shifted from being predominately ASPN− in benign prostate stroma to being comparably ASPN− and ASPN+ in the cribriform prostate tumor microenvironment." (PMID 33600062, 2021). "All prostate tumors were found to be hypermethylated in both ALOX12 and PDGFRB, while the 2 BPH samples remained unmethylated (Spearman coefficient 0.67 and 0.78 respectively)." (PMID 24626295, 2014).
pulmonary emphysema (5 papers, 2013 to 2022). A subcategory of chronic obstructive pulmonary disease (COPD). "Sesn2 may also inhibit PDGFRβ expression and in another study, it was demonstrated that the development of cigarette-smoke-induced pulmonary emphysema was prevented by the mutational inactivation of Sesn2 through the up regulation of PDGFRβ expression." (PMID 36040980, 2022). "This reduces the pulmonary susceptibility to emphysema induced by tobacco smoke, which upregulates Sesn2 expression and thus suppresses the alveolar maintenance programmes controlled by PDGFRβ." (PMID 24046361, 2013). "In mice, the mutational inactivation of Sesn2 prevents the development of cigarette-smoke-induced pulmonary emphysema by upregulating PDGFRβ expression via a selective accumulation of intracellular superoxide anions (O2−)." (PMID 24046361, 2013). "Groups of mice with elastase-induced emphysema were treated either with placebo or with the PDGFRβ inhibitor imatinib." (PMID 24046361, 2013). "Interestingly, in a similar animal study, the mutational inactivation of Sestrin 2 prevented the development of cigarette-smoke-induced pulmonary emphysema by upregulating platelet-derived growth factor receptor β PDGFRβ expression." (PMID 32050426, 2020). "To investigate whether PDGFRβ is important in the overall pathogenesis of emphysema, we employed the smoke-independent elastase-induced emphysema model." (PMID 24046361, 2013). "However, it was shown that attenuation of ROS, particularly superoxide anions through Sestrin2/Nrf2 signaling, can downregulate TGF-β/Smad and platelet-derived growth factor receptor-beta (PDGFRβ) and enhance cigarette smoke-mediated emphysema in the mice model." (PMID 34765085, 2021).
synovial sarcoma (5 papers, 2016 to 2026). "Most cases of synovial sarcoma (45.8%) and 43.7% of patients with undifferentiated sarcoma exhibited high expression of PDGFRα while 41.6% of MPNST showed high expression to PDGFRβ." (PMID 39534097, 2024).
aneurysm (4 papers, 2021 to 2025). Bulging or ballooning in an area of an artery secondary to arterial wall weakening. "Notably, PDGFRb deletion in CD34+ cells not only promoted AAA progression but also significantly increased the mortality rate of aneurysms." (PMID 39731355, 2025). "Collectively, although both PDGFRs in CD34+ cells play important roles in CD34+ cell proliferation and AAA progression, PDGFRb, rather than PDGFRa, is required for CD34+ cell transdifferentiation into Periostin+ myofibroblasts, thereby protecting aneurysms from rupture." (PMID 39731355, 2025).